ATG5 (autophagy related 5)
Diseases named in the same sentence as ATG5 in open-access papers (continued):
Sharing a sentence is not in itself a finding about the gene and the disease.
atherosclerosis (28 papers, 2012 to 2023). A disease characterized by the build-up of fatty material and calcium deposition in the arterial wall resulting in partial or complete occlusion of the arterial lumen. "Macrophage-specific Atg5 deficiency promotes atherosclerosis by interfering with cholesterol transport, apoptosis, and inflammation." (PMID 33837179, 2021). "In mice with a macrophage-specific ablation of ATG5, P62 deficiency increases atherosclerotic plaque burden, indicating ATG5 involvement in atherosclerosis formation." (PMID 32377431, 2020). "Macrophages from Atg5 knockout mice have increased susceptibility to death indicating that autophagy reduces advanced atherosclerosis induction of macrophage death." (PMID 28163707, 2017). "Macrophage-specific deficiency of Atg5 accelerated the development of atherosclerosis in Apoe−/− mice by insufficient autophagy in cells." (PMID 29270409, 2017). "In the case of atherosclerosis, autophagic defects caused by Atg5 deficiency reduced the efficiency of the efferocytic clearance of dead cells, leading to an expansion of the necrotic core." (PMID 29270409, 2017). "Accordingly, macrophage-specific Atg5 deficiency augmented the expansion of lesional necrotic cores and progression of atherosclerosis." (PMID 29270409, 2017). "Furthermore, in a macrophage-specific ATG5 knockout mice model, the study shows that autophagy becomes dysfunctional in atherosclerosis, and its deficiency promotes atherosclerosis in part through inflammasome hyperactivation." (PMID 30572675, 2018). "It seems to play a protective role in the early phase of atherosclerosis, as deletion of autophagy genes (Atg5) accelerates the progression of atherosclerosis in murine models." (PMID 37198605, 2023). "Recent studies have found that PDCD4 negatively regulates autophagy by inhibiting the expression of ATG5 in tumour cells and plays a certain role in autophagy in the treatment of atherosclerosis." (PMID 37461031, 2023). "By contrast, atherosclerosisoccurs and is exacerbated by impaired or defective autophagy in macrophages.Defects in macrophage ATG5 promote apoptosis and oxidative stress in macrophages,and worsen lesional efferocytosis in advanced atherosclerosis." (PMID 39077721, 2022). "In addition, to validate whether NET-mediated suppression of macrophage autophagy plays an important role for developing atherosclerosis in vivo, loss-of-function animal models such as macrophage-specific Atg5 knockout mice should be crossed with ApoE−/−; Neu-Pad4−/−mice." (PMID 35923856, 2022). "Inhibition of autophagic factors, such as ATG5, increases atherosclerosis in hypercholesterolemic mice, and excess dietary protein in these models has recently been found to exacerbate atherosclerosis by a mTOR dependent inhibition of autophagy." (PMID 33984028, 2021). "Previous reports show that defective phagocytic clearance of macrophages promotes plaque necrosis and inhibition of autophagy by silencing ATG5 or other autophagy mediators to enhance protective processes in atherosclerosis." (PMID 30627532, 2018). "In early lesions of atherosclerosis, CysC expression was mainly seen in endothelial cells and in intimal areas, which were positive for the autophagy marker Atg5, to some extent for p62/SQSTM1 and for ubiquitin." (PMID 27079462, 2016). "MiR-214-3p regulates ox-LDL-initiated EC autophagy by directly targeting 3′-UTR of ATG5, which may play an appropriate role in the pathogenesis of atherosclerosis." (PMID 35096837, 2021). "However, macrophage-specific Atg5 knockout mice on the Apoe-/- background (Atg5-mφ Apoe-/-) developed dramatically worse atherosclerosis." (PMID 26847458, 2016). "To study whether the lack of CysC in mice had any effect on autophagy and cell death in atherosclerosis, we analysed Atg5 and LC3β for autophagy and TUNEL for apoptosis in lesions in apoE−/−CysC−/− compared with apoE−/−CysC+/+ mice." (PMID 27079462, 2016).
atherosclerosis (continued). "Furthermore, GDF15, in combination with oxLDL, positively regulates the expression of autophagy‐related proteins such as Atg5, p62 and the Atg12/Atg5 protein complex and elicits p62 accumulation in human macrophages, thus promoting lipid accumulation and, therefore, atherosclerosis development." (PMID 36992609, 2023). "In addition, the overexpression of miR-214-3p could promote atherosclerosis by directly targeting ATG5." (PMID 37248458, 2023). "Some studies suggest that it is a protective factor against atherosclerosis, and that autophagy is inhibited in patients with cardiovascular disease, featured by the decrease of LC3 and Atg5 genes." (PMID 35152560, 2022). "Deacetylation of autophagy protein 5 (ATG5) by SIRT1 activates ATG5 to increase autophagy, which protects from atherosclerosis." (PMID 35529430, 2022). "In macrophage foam cell from atherosclerosis model, SIRT6 and key autophagy effectors (ATG5, LC3B, and LAMP1) had been observed significantly and the overexpression of SIRT6 markedly reduced foam cell formation by inducing autophagy." (PMID 33855020, 2021). "Therefore, we used different analyses (activity assays, TEM) and autophagy-relevant markers (ATG5, p62) to investigate and verify the influence of GDF-15 on the autophagic pathway in atherosclerosis." (PMID 34571994, 2021). "The absence of ATG5 or p62 abrogates TFEB's ability to reduce atherosclerosis, plaque complexity, macrophage apoptosis and aggrephagy of p62-enriched protein aggregates." (PMID 28589926, 2017). "Consistent with TFEB's dependence on autophagy, the dual mφTFEB-TG/ATG5-KO mice were no longer protected from atherosclerosis with similar serum cholesterol and other common serum metabolites to controls." (PMID 28589926, 2017). "Our findings with dual mφTFEB-TG/ATG5-KO macrophages were mirrored with dual mφTFEB-TG/p62-KO mice where again TFEB's protective effects on atherosclerosis and lesion complexity were abrogated in the absence of p62." (PMID 28589926, 2017). "The silencing of the key autophagy initiation gene ATG5 reversed the autophagy-promoting effect of SIRT6 with an increase in foam cells, which implied an autophagy-dependent pathway of SIRT6 in protecting against atherosclerosis by reducing foam cell formation." (PMID 33855020, 2021). "Collectively, the altered ATG5 level may influence lipid metabolism and inflammation through its autophagic and nonautophagic function, contributing to atherosclerosis and its complications." (PMID 32377431, 2020).
viral infection (28 papers, 2009 to 2025). "ATG5 has a key role in autophagic vesicles and has been directly implicated in immunomodulatory effects in the course of other viral infections, and its upregulation was consistent from immediately after therapy began." (PMID 34369652, 2021). "We observed that the leaf curl symptoms caused by viral infection were much more severe and appeared 3 days earlier, and CLCuMuV DNA levels were significantly higher in ATG5- and ATG7- silenced plants compared to control plants." (PMID 28244873, 2017). "IRGM also has been confirmed to be associated to mitochondria and interact with autophagy-associated proteins (ATG5) directly upon virus infection." (PMID 25853521, 2015). "Similarly, it should benoted that in this context, Atg5 deficient cells demonstrate increasedinterferon protection and increased protection from viral infection rather thanthe usual situation where autophagy disruption results in a loss of functionphenotype." (PMID 20157526, 2009). "Alongside LC3-II, which is a key molecule in autophagosomal membrane formation via the Atg5-Atg12/Atg16 complex, Atg5 also plays an essential role in various biological processes such as viral infection, tumor apoptosis, and tumor proliferation." (PMID 40248706, 2025). "Applying the autophagy inhibitor 3-methyladenine or silencing the expression of ATG5 significantly decreases viral infection, whereas applying the autophagy inducer rapamycin facilitates viral infection." (PMID 35533206, 2022). "Taken together, these results reveal that eIF4A negatively regulates antiviral autophagy by interacting with ATG5 and that its mRNA is recognized by a virus-derived siRNA, resulting in its silencing, which induces autophagy against viral infection." (PMID 34587220, 2021). "Defects in the molecular machinery for macroautophagy, such as the genetic inhibition of ATG5 or beclin-1 (BECN1) genes, consequently make mice and primary human astrocytes more susceptible to viral infections." (PMID 33920748, 2021). "These authors also showed that the virus infection not only induced both ATG12–ATG5 conjugation as well as the conversion of LC3-I to LC3-II, but also led to significant increases in ATG5 and BECN1 levels within cells infected with the CSFV virus." (PMID 31744077, 2019). "Taken together, the results from this study suggest that autophagy, and particularly Atg5 gene, is involved in the clearance of viral proteins against host viral infection." (PMID 31291924, 2019). "Inparticular, ROS appeared to mediate the increase in interferon secretion andresistance to viral infection seen in Atg5-/- cells." (PMID 20157526, 2009). "Mechanistically, ATG5 promotes K48-linked polyubiquitination and autophagy to degrade RIG-I and MDA5, resulting in decreased IRF7 phosphorylation and subsequent attenuation of the acute immune-inflammatory response during viral infection." (PMID 40454785, 2025). "ATG5 is known to pay a role in immune response against viral infection." (PMID 37620383, 2023). "The functional distinction of ATG5 and autophagy during virus infection may be attributed to species and virus specificity." (PMID 32911775, 2020). "Moreover, ATG5 interacts transiently with the HCV RNA polymerase as a proviral factor during the onset of viral infection." (PMID 31216340, 2019). "Silencing of ATG5 and ATG7 caused more severe disease symptoms and enhanced viral DNA accumulation compared to the control, and silencing of GAPCs reduced the severity of viral disease symptoms and viral DNA levels in plants infected by TYLCV or TYLCCNV." (PMID 28244873, 2017).
viral infection (continued). "Consistent with a protective role of autophagy in neurons, over-expression of Beclin 1 significantly improves motor symptoms in a mouse model of Machado-Joseph disease or spinocerebellar ataxia type 344, and expression of Atg5 protects neurons against virus infection-induced cell death." (PMID 26987296, 2016). "The expression level of the autophagy gene (ATG-5, ATG-7 and LC3) increased significantly after the virus infection." (PMID 39403204, 2024). "On the other hand, ATG5 can also obstruct viral infections by playing a pivotal, non-degradative role in IFNγ-mediated antiviral defenses." (PMID 38915300, 2024). "While the lack of basal autophagy in LC3B knockout glial cells does not have a significant effect on viral infection, cells without the autophagy-related protein ATG5 exhibit reduced viral production." (PMID 38915300, 2024). "Regarding viral infections, the non-canonical functions of ATG5 can be exploited to enhance viral replication." (PMID 38915300, 2024). "Thus, ATG5 was required for RGDV-induced ATG8 lipidation, autophagosome formation and efficient viral infection and transmission in the insect vectors." (PMID 35533206, 2022). "We confirmed that IAV induced autophagosome formation and p62 accumulation in infected cells and demonstrated that perturbation of autophagy did not impact viral infection or replication in ATG5-stablized cells." (PMID 29748576, 2018). "It has been reported that plasmacytoid dendritic cells deficient in Atg5, or treated with autophagy inhibitors, failed to produce IFN-α in response to viral infection." (PMID 25029098, 2014). "Atg5, though indispensible for autophagy, has functions independent of autophagy including a role in apoptosis and regulation of interferon (IFN) responses against viral infections." (PMID 22536318, 2012). "Moreover, CVB3 replication was not impaired in ATG5 KO HeLa cells, in which autophagosome formation is restricted, confirming that viral infection proceeds independently of autophagy." (PMID 41471369, 2025). "However, recent research indicates that the role of this protein in viral infections is more complex than previously thought, and the participation of ATG5 in non-autophagic processes is attracting increasing interest." (PMID 38915300, 2024). "Thus, the autophagosome-related p62 and ATG5 were not degraded after viral infection in R. dorsalis." (PMID 35533206, 2022). "In contrast, silencing of ATG5 or ATG7 did not affect viral infection." (PMID 29593293, 2018). "Furthermore, silencing of autophagy-related genes ATG5 and ATG7 reduced plant resistance to the DNA viruses CLCuMuV, Tomato yellow leaf curl virus, and Tomato yellow leaf curl China virus, whereas activating autophagy by silencing GAPC genes enhanced plant resistance to viral infection." (PMID 28244873, 2017). "In fact, it was previously shown that ATG5 or ATG7 are not required for mouse hepatitis virus or SARS-CoVs replication, since knocking out of these genes did not inhibit viral infection." (PMID 33920748, 2021).
cardiac hypertrophy (26 papers, 2013 to 2025). "Although no studies have yet explored the consequences of disrupted cardiac ATG7 expression, familial ATG5 mutations are associated with severe cardiac hypertrophy leading to dilated cardiomyopathy by 10 months." (PMID 36939901, 2023). "Global atg5 knockout mice have embryonic or neonatal death and cardiac-specific atg5 deficiency led to cardiac hypertrophy, left ventricular dilatation, and contractile dysfunction." (PMID 33915953, 2021). "Cardiac-specific Atg5 deficiency mice exhibited worse cardiac function and more serious cardiac hypertrophy after pressure overload for 1 week compared with wild type mice." (PMID 34749750, 2021). "Cardiac-specific deficiency of atg5 led to cardiac hypertrophy, left ventricular dilatation, and contractile dysfunction in adult mice." (PMID 33915953, 2021). "In fact, cardiac-specific deficiency of Atg5 (autophagy-related 5) in mice or β-adrenergic stimulation, facilitates myocardial hypertrophy, whereas rapamycin-induced autophagic activation can prevent it." (PMID 28751931, 2017). "For example, cardiac specific loss of autophagy-related 5 (Atg5) in mice was shown to cause cardiomyopathy and cardiac hypertrophy associated with contractile dysfunction, disorganized sarcomeres, and accrual of dysfunctional mitochondria." (PMID 29257072, 2017). "Conditional knockout of Atg5 in the heart causes a disruption in autophagy, and results in cardiac hypertrophy and contractile dysfunction." (PMID 27512143, 2016). "In addition, cardiomyocyte-specific deletion of Atg5 caused cardiac hypertrophy and dysfunction, and cardiomyocyte-specific deletion of Atg7 caused cardiac systolic dysfunction and reduced the survival of mice." (PMID 37733896, 2024). "In addition, inhibition of autophagy was associated with the development of cardiac hypertrophy in response to the cardiac-specific deletion of Atg5 in mouse cardiomyocytes." (PMID 31885498, 2019). "Cardiac-specific Atg5 or Atg7 deficiency leads to cardiac hypertrophy." (PMID 23737997, 2013). "Thus, atg5 deletion clearly led to cardiac autophagy deficiency, cardiac hypertrophy, and fibrosis." (PMID 33915953, 2021). "In the present study, we found that increased Atg3 and Atg5 levels in the heart of rats with Ang II-induced cardiac hypertrophy were suppressed after downregulation of salusins." (PMID 38336819, 2024). "Valsartan inhibits excessive mitophagy and alleviates ventricular hypertrophy by modulating autophagy-related genes, such as Atg5." (PMID 38239871, 2023). "Knockout of the ATG5 gene leads to myocardial cell necrosis and increased cross-sectional area of myocardial cells, indicating that ATG5 is involved in myocardial hypertrophy and obesity, and the regulation of lipid metabolism." (PMID 37304955, 2023). "In this regard, during the cardiomyocyte-specific knockout of ATG5 implemented to block the autophagy pathway in the mouse model, the mice developed left ventricular dilation, systolic dysfunction, and cardiac hypertrophy and incurred death at about 10 months." (PMID 37445978, 2023). "In this regard, cardiac-specific Atg5 (autophagy-related 5) knockout mice showed abnormal cardiac function, characterized by the disorganized sarcomere, mitochondrial misalignment and aggregation, and cardiac hypertrophy." (PMID 37445978, 2023). "In cardiomyocytes, the immunoproteasome β5i subunit interacts with ATG5 to promote the ubiquitination and degradation of ATG5, thereby inhibiting autophagy and leading to cardiac hypertrophy." (PMID 35806307, 2022). "ATG5 knockout mice, since ATG5 is necessary for optimal autophagy, develop cardiac hypertrophy, dilated cardiomyopathy, and contractile dysfunction with the accumulation of ubiquitinated proteins, chaotic sarcomere structures, and mitochondrial aggregation." (PMID 34341709, 2021). "Next, we explored the impact of the deletion of atg5 in cardiomyocytes on myocardial hypertrophy and cardiac fibrosis." (PMID 33915953, 2021).
cardiac hypertrophy (continued). "We observed that fibroblast-specific deletion of the autophagic gene Atg5 effectively reduced cardiac fibrosis in a mouse model of cardiac hypertrophy." (PMID 33668422, 2021). "Recently, we revealed that LMP7 can interact with and promote the degradation of ubiquitinated ATG5, which inhibits autophagy, thereby leading to pressure overload- or Ang II-induced cardiac hypertrophy." (PMID 32581853, 2020). "For example, impaired autophagy by knocking Atg5 out leads to cardiac hypertrophy and contractile dysfunction." (PMID 27512143, 2016). "Notably, the β5i subunit has been shown to promote cardiac hypertrophy, heart failure, and AF by targeting the autophagy-related protein ATG5 for degradation, thereby suppressing autophagic activity." (PMID 41614876, 2025). "In addition, β5i serves as a critical modulator of autophagy and cardiac hypertrophy by promoting the degradation of ATG5, thereby suppressing autophagic activation and leading to cardiac hypertrophy and dysfunction." (PMID 41614876, 2025). "Upregulation of immunoproteasome catalytic subunit β5i leads to cardiac hypertrophy and heart failure (HF) by promoting ATG5 degradation, while Nrf2 ablation slows the progression of diabetic cardiomyopathy (DC) in cardiomyocyte-specific ATG5 KO mice." (PMID 36312227, 2022). "In addition, melatonin prevented myocyte apoptosis and autophagy dysfunction by Atg5‐ and Akt/mTOR‐dependent pathways in pressure overload‐induced cardiac hypertrophy." (PMID 35170783, 2022). "Beclin1 and Atg5 are two autophagy-related (Atg) proteins, however they show a different result between Becn1+/− mice with alleviative myocardial remodeling and Atg5+/− mice with aggravating myocardial hypertrophy in pathological myocardial remodeling." (PMID 35534453, 2022). "The impairment of autophagy does not cause any manifestations in Atg5-deficient hearts in early cardiogenesis, while in adult animals, cardiac hypertrophy, LV dilatation, and contractile dysfunction are developed." (PMID 35011735, 2022). "Using a cardiac hypertrophy model induced by continuous infusion of angiotensin II with osmotic minipumps, we confirmed that mice lacking either Fosl-2 (Ccl19CreFosl2flox/flox) or Atg5 (Ccl19CreAtg5flox/flox) in stromal cells were protected from cardiac fibrosis." (PMID 33668422, 2021).